RNU6-89P (RNA, U6 small nuclear 89, pseudogene)
Gene: Small nuclear RNA gene on chromosome 1 (202,410,108 to 202,410,207, reverse strand). Ensembl gene ENSG00000272262.
Homologues: Orthologues: chimpanzee U6 (100% identical), macaque U6 (96% identical), mouse Gm22281 (82% identical), guinea pig U6 (79% identical), dog U6 (78% identical), rabbit U6 (76% identical), rat LOC120095360 (75% identical). Paralogues in human: RNU6-1314P (97% identical), RNU6-38P (92% identical), RNU6-1011P (91% identical), RNU6-1145P (90% identical), RNU6-15P (90% identical), RNU6-639P (90% identical), RNU6-20P (89% identical), RNU6-29P (89% identical), RNU6-33P (89% identical), RNU6-345P (89% identical), RNU6-393P (89% identical), RNU6-476P (89% identical), and 1288 more.